PRKDC (protein kinase, DNA-activated, catalytic subunit)
Diseases named in the same sentence as PRKDC in open-access papers (continued):
Sharing a sentence is not in itself a finding about the gene and the disease.
melanoma (36 papers, 2010 to 2026). A malignant, usually aggressive tumor composed of atypical, neoplastic melanocytes. "The increased TMB and neoantigen load in melanoma patients with PRKDC mutations or deletions supports our findings that DNA-PKi not only increases the expression of neoantigen transcripts but also induces what we considered to be a new panel of neoantigens." (PMID 39436696, 2024). "We also found that the amplification rates of PRKDC were significantly higher in AMs and MMs than in CMs (49% in AMs, 63% in MMs and 18% in CMs) and were confirmed to be associated with patient clinical outcomes in all three histological types of melanomas, consistent with previous studies." (PMID 39039072, 2024). "As a result, PRKDC amplification was the most significant predictive factor for the prognosis of melanoma patients." (PMID 39039072, 2024). "Further analysis revealed that amplification of the DNA damage repair-related kinase PRKDC was a potential prognostic molecule for melanoma." (PMID 39039072, 2024). "Our data reveal that in patients with melanoma who received anti–PD-1/–CTLA-4 blockade, PRKDC mutations were associated with a higher TMB, neoantigen loads, and enhanced responses." (PMID 39436696, 2024). "Our data indicate that in patients with melanoma, reduced PRKDC levels correlated with increased CD8+ TILs and MHC-I expression, both of which are strong indicators of a response to immunotherapy." (PMID 39436696, 2024). "To uncover associations between CD8 infiltrates and the expression of MHC-I (HLAA) with PRKDC (DNA-PK) levels, we analyzed melanoma patient data from The Cancer Genome Atlas (TCGA)." (PMID 39436696, 2024). "Knockdown of PRKDC using small interfering RNA increased the sensitivity of malignant melanoma cells to cisplatin treatment." (PMID 35054819, 2022). "PRKDC was ranked as top genes by DADA and showed direct interactions with both known CMM susceptibility genes and melanoma driver genes." (PMID 33057211, 2020). "Thus, we reviewed publicly available exome-sequencing data from patients with melanoma undergoing CTLA-4 or PD-1 blockade therapy to investigate potential correlations between PRKDC levels and response to checkpoint therapy." (PMID 39436696, 2024). "Interestingly, several exclusively mutated genes in murine dormant cells such as ZFPM2, PRKDC, TDRD1, NES, CDC42BPBD and HX57, exhibited moderate to high frequencies of mutation in human melanoma." (PMID 39223638, 2024). "We evaluated the potential therapeutic potential of targeting PRKDC to enhance the efficacy of immunotherapy and confirmed the potential therapeutic options involving the use of PRKDC inhibitors combined with anti-PD-1 therapy for melanoma treatment in the future." (PMID 39039072, 2024). "In our study, we found that PRKDC amplification was a prognostic marker for melanoma." (PMID 39039072, 2024). "Notably, since we observed that both the S-II and S-III subgroups were associated with poor prognosis, we evaluated the expression of PRKDC (an independent prognostic molecule of melanoma) among the three proteomic subtypes." (PMID 39039072, 2024). "Multivariate analysis reveals that PRKDC amplification is a prognostic molecule for melanomas." (PMID 39039072, 2024). "Therefore, we collected primary tumor cell cultures (PDCs) from SBS7a+ and SBS7a– patients (Melanoma #8, Melanoma #14: SBS7a+ patients; Melanoma #9, Melanoma #19: SBS7a– patients) and evaluated the response of PDCs to PRKDC inhibitor (NU7441)." (PMID 39039072, 2024). "In contrast, PRKDC may reduce the sensitivity of melanoma patients to immunotherapy by promoting DNA repair in melanoma cells." (PMID 39039072, 2024). "Moreover, we found that PRKDC might reduce the sensitivity of melanoma patients to immunotherapy by promoting DNA repair and cell proliferation." (PMID 39039072, 2024).
melanoma (continued). "Moreover, for mice transplanted with MAPK7-KD-A375 cells, compared to PD-1 treatment alone, the combination of PRKDC and a PD-1 inhibitor significantly reduced tumor growth, confirming the potential of using a PRKDC inhibitor combined with an anti-PD-1 antibody for melanoma treatment in the future." (PMID 39039072, 2024). "As a result, the sensitivity to 5-FU showed the most significant positive correlation with the protein expression of PRKDC (5-FU: Spearman’s r = 0.77, p = 0.026), suggesting that melanoma patients who harbor PRKDC amplicons might be more sensitive to 5-FU treatment." (PMID 39039072, 2024). "Additionally, previous studies reported that other genes are frequently mutated in melanoma and other cancer types, including BRCA2 (9/112, 8%), LRP1B (9/112, 8%), MET (8/112, 7%), PRKDC (7/112, 6%), NOTCH4 (7/112, 6%), CCND3 (6/112, 5%), and FGF3/4/19 (6/112, 5%)." (PMID 37649078, 2023). "Moreover, miR-488-3p could regulate protein kinase, DNA-activated, catalytic subunit (PRKDC) and sensitize malignant melanoma cells to cisplatin." (PMID 32862195, 2021). "In another two cohorts, a total of two patients (study IDs were CR4880 and PR4092,) with melanoma who received anti‐CTLA4 therapy and one patient with lung adenocarcinoma (study ID was DI6359,) who received anti‐PD‐1 therapy were verified to harbor PRKDC mutations." (PMID 32502294, 2020). "We then profiled the proteomes of four types of melanoma cells with different PRKDC expression patterns, namely, Vector-OE-high (OE-Control-HMCB), PRKDC-OE-HMCB, Scramble-shRNA-HMCB (sh-Control-HMCB), and PRKDC-KD-HMCB." (PMID 39039072, 2024). "In patients with melanoma treated with anti–PD-1 and anti–CTLA-4, DNA-PK (PRKDC) transcript levels inversely correlated with CD8 and MHC-I transcript levels, whereas mutations in DNA-PK correlated with increased tumor mutation burden (TMB) and neoantigen load." (PMID 39436696, 2024). "In subgroup III, CDK4 amplification and PRKDC amplification jointly promoted increased CDK4 protein expression and kinase activity in melanoma patients, accelerating the proliferation rate of melanoma and leading to poor prognosis." (PMID 39039072, 2024). "As a newly identified miRNA, miR-488-3p was found as a tumor suppressor in esophageal squamous cell carcinoma and melanoma by respectively targeting ZBTB2 and PRKDC." (PMID 32862195, 2021). "Further integrative analysis revealed that patients harboring SBS7a had significantly elevated expression of DNA damage repair-related proteins, such as PRKDC, ATR, and POLD4, suggesting that elevated DNA damage repair contributes to poor prognosis in patients with melanoma." (PMID 39039072, 2024). "Specifically, PRKDC amplification coupled with CDK4 amplification increased cell proliferation in S-II, whereas ROCK2 amplification elevated the increased angiogenesis and promoted melanoma metastasis in S-III." (PMID 39039072, 2024). "In a melanoma cell line model, it has been shown that mutant BRAF inhibition may increase DNA damage by downregulation of NHEJ pathway genes, including XRCC6, XRCC5, and PRKDC." (PMID 33195430, 2020).
cervical carcinoma (32 papers, 2000 to 2025). A carcinoma arising from either the exocervical squamous epithelium or the endocervical glandular epithelium. "Functional studies of PRKDC expression in relation to chemosensitivity and as a possible target for treatment in cervical cancer would therefore be of high interest." (PMID 34620846, 2021).
colon carcinoma (28 papers, 2008 to 2025). "To identify novel functions for DNA-PKcs activity in human cells, we utilized a rAAV-mediated gene targeting strategy to introduce a point mutation in the DNA-PKcs gene (PRKDC) that inactivates the kinase domain of DNA-PKcs in the human colon carcinoma cell line HCT116." (PMID 31396623, 2019). "Therefore, the collective data along with our results validate PRKDC overexpression as a potential therapeutic target in colon cancer." (PMID 33195430, 2020). "Thus, PRKDC inhibition in addition to irinotecan treatment might be particularly beneficial in colon cancers with PTEN inactivation." (PMID 34065438, 2021). "This analysis revealed upregulation of XRCC5, PRKDC, and PAXX in colon cancer compared to normal colon tissues, while LIG4 and NHEJ1 (XLF) displayed downregulation." (PMID 33195430, 2020). "To determine the expression pattern of core NHEJ genes in colon cancer, we performed Oncomine analysis for XRCC6 (Ku70), XRCC5 (Ku80), PRKDC (DNA-PKcs), XRCC4 (XRCC4), LIG4 (DNA ligase 4), NHEJ1 (XLF), and PAXX (PAXX/XLS)." (PMID 33195430, 2020). "PRKDC exhibited overexpression in Oncomine analysis, TCGA dataset as well as CPTAC study suggesting consistent overexpression of this protein in colon cancer, both at the mRNA and protein levels." (PMID 33195430, 2020). "Moreover, the interaction between PRKDC and KRT80 protein accelerated invasion in colon cancer 9, and OTUB2 influenced KRT80 stability through deubiquitination, promoting the malignancy of gastric cancer." (PMID 38495507, 2024). "Our analysis revealed that BRAF mutant colon cancer did not harbor higher NHEJ1 expression compared to BRAF wild type tumors and three NHEJ pathway genes, XRCC5, PRKDC, and LIG4 are indeed lowly expressed in BRAF mutant tumors." (PMID 33195430, 2020). "Since the molecular testing of colon tumors for MLH1, and not MSH3 expression, is a clinical standard, they proposed that MLH1 is a much better marker to be assessed for a more significant number of patients to benefit from PRKDC inhibition." (PMID 34065438, 2021).
gastric cancer (25 papers, 2011 to 2025). A primary or metastatic malignant neoplasm involving the stomach. "Our results reveal an oncogenic role played by hsa_circ_0136666 in gastric cancer, driving PD-L1 phosphorylation via the miR-375/PRKDC signaling axis, prompting immune escape." (PMID 38093288, 2023). "In gastric cancer, PRKDC was identified as the top upregulated DNA damage repair gene, and high expression of PRKDC was associated with poor survival." (PMID 36672781, 2022). "In our study, PRKDC was up-regulated (at least a two-fold change in the gene expression level) in 64% (16/25) of gastric cancer samples." (PMID 22559327, 2012). "Through miR-375, hsa_circ_0136666 promotes the expression of PRKDC, which can phosphorylate PDL1 and enhance its stability, thereby promoting gastric cancer progression and immune escape." (PMID 38093288, 2023). "Interestingly, four of the identified key genes (CDK6, MCM2, PRKDC, and CCNE1) are on the cell cycle pathway, underscoring the importance of this process in gastric cancer." (PMID 28603669, 2017).
hepatocellular carcinoma (23 papers, 2013 to 2026). A malignant tumor that arises from hepatocytes. "PRKDC, PARP1, NPM1 and XRCC6 are hepatocellular carcinoma over-expression genes which modulate cell cycle regulation network through the modulation of UBC." (PMID 24564241, 2013).
viral infection (20 papers, 2010 to 2025). "Remarkably, cells from SCID mice with a loss-of-function mutation in PRKDC and patients with PRKDC missense mutations have a signature of stronger innate immune and inflammatory gene expression at basal level and in response to viral infection, making them more resistant to viral challenge." (PMID 33273464, 2020). "RNAseq and protein expression analysis ofDDB2,RAD17,PRKDC,PCNA and other ATR pathway markers of infected cells accompanied by time course studies of nascent double stranded chromosomal breaks (i.e. H2AX antibody staining due to viral infection) would provide such evidence." (PMID 33299552, 2020).
nasopharyngeal carcinoma (17 papers, 2012 to 2025). A carcinoma arising from the nasopharyngeal epithelium. "In our clinic, we treated a patient (NPC_Y) with stage IVA nasopharyngeal carcinoma that harbored a PRKDC mutation." (PMID 32502294, 2020).
pancreatic cancer (15 papers, 2015 to 2025). "PRRX1, along with the cofactor FOXM1, was reported to activate the transcription of PRKDC, the gene encoding DNA-PKcs, in pancreatic cancer cells." (PMID 40114375, 2025). "All these findings show PRKDC inhibition increases effective inhibitory concentration of RP-6306 and suppresses RP-6306-induced cytotoxicity and cell death in pancreatic cancer cells." (PMID 38570712, 2024). "Interestingly, PRRX1 could transcriptionally maintain the expressions of DDR genes including ATM, ATR, BRCA1, PRKDC, and XRCC1, in PANC1 pancreatic cancer cells." (PMID 40114375, 2025).
autoimmune disease (12 papers, 2012 to 2025). A disorder resulting from loss of function or tissue destruction of an organ or multiple organs, arising from humoral or cellular immune responses of the individual to their own tissue constituents. "Studies show that PRKDC mutation influenced production T/B cells and V(D)J rearrangement, which act as major triggers of auto-antibodies and autoimmune disease production." (PMID 37580814, 2023). "Missense mutations of PRKDC encoding the DNA-dependent protein kinase (DNA-PK) catalytic subunit (DNA-PKcs) are associated with autoimmune diseases, yet how DNA-PK deficiency leads to increased immune responses remains poorly understood." (PMID 33273464, 2020). "The DNA-dependent protein kinase (DNA-PK) catalytic subunit (DNA-PKcs) encoded by the missense mutations of protein Kinase, DNA-activated, catalytic Subunit (PRKDC) are associated with autoimmune diseases due the overactivated enzymatic activity of the cGAS." (PMID 33643304, 2020). "This study may provide explanations for why missense mutations of PRKDC, the DNAPK catalytic subunit, are observed in patients with autoimmune diseases." (PMID 35795661, 2022). "PRKDC mutation leads to SCID due to V(D)J recombination defect, and patients develop into autoimmune diseases because of overactivated innate immunity." (PMID 38898995, 2024). "PRKDC mutation is seldom reported on autoimmune diseases and no related studies on SLE, especially for the treatment and prognosis of SLE with this gene mutation." (PMID 37580814, 2023). "Moreover, as described in the literature for PRKDC and ORAI1, mutations within SERPING1 can also cause severe forms of inflammatory and autoimmune disorders." (PMID 36294757, 2022). "Additionally, PRKDC (cg22338356, associated with the maternal PGS for height), one of the two genes with significantly regulated protein expression in the dlPFC in schizophrenia, is highly expressed in immune cells and mutations have been linked to autoimmune diseases and increased immune response." (PMID 40181191, 2025).
lymphoma (12 papers, 2013 to 2024). A malignant (clonal) proliferation of B- lymphocytes or T- lymphocytes which involves the lymph nodes, bone marrow and/or extranodal sites. "We examined c-MYC protein expression levels in lymphoma cell lines treated with the PRKDC inhibitor, KU0060648." (PMID 25495526, 2014). "We also analysed the phosphoproteomic dataset from Eμ-Myc Rel−/− lymphomas for evidence of any general changes in ATR, Ataxia Telangiectasia Mutated (ATM) or DNA-Dependent Protein Kinase (DNA-PK, PRKDC) dependent phosphorylation, whose target phosphosites generally contain an SQ or TQ motif." (PMID 36240066, 2022). "In order to further validate PRKDC dependency in other MYC-driven cancers, we chose to examine c-MYC in human lymphoma cell lines using the potent PRKDC inhibitors, NU-7441 and KU0060648." (PMID 25495526, 2014).
osteosarcoma (12 papers, 2008 to 2025). A usually aggressive malignant bone-forming mesenchymal neoplasm, predominantly affecting adolescents and young adults. "We demonstrated that YTHDF1 knockdown decreased PRKDC mRNA and DNA‐PKcs protein levels and reversed the changes in osteosarcoma sensitivity to anlotinib induced by METTL3 overexpression." (PMID 39924638, 2025). "Altogether, these results confirm that YTHDF1 regulates METTL3‐mediated PRKDC m6A modification, contributing to the maintenance of anlotinib resistance in osteosarcoma." (PMID 39924638, 2025). "Consistent with the effects observed following si‐PRKDC treatment, PRKDC shRNA significantly potentiated the reaction of osteosarcoma cells to anlotinib." (PMID 39924638, 2025). "Functionally, METTL3 enhances anlotinib resistance in osteosarcoma, which is reversed by PRKDC knockdown." (PMID 39924638, 2025). "Inhibition of PRKDC in osteosarcoma cell lines increased radiosensitivity, while co-treatment with the PRKDC inhibitor KU60648 resulted in enhanced DNA damage." (PMID 35054819, 2022). "However, the downstream ‘reader’ of PRKDC m6A modification in osteosarcoma remains elusive and necessitates further investigation." (PMID 39924638, 2025). "We evaluated the effects of si‐PRKDC treatment alone on autophagy in osteosarcoma cells." (PMID 39924638, 2025). "Furthermore, there was an increase in the percentage of apoptotic osteosarcoma cells in the si‐PRKDC+ anlotinib group relative to that in the group receiving anlotinib alone, as detected via flow cytometry." (PMID 39924638, 2025). "Hence, we hypothesised that YTHDF1 might serve as a ‘reader’ of PRKDC m6A methylation, thereby affecting the sensibility of osteosarcoma cells to anlotinib." (PMID 39924638, 2025). "Additionally, we explored whether the m6A modification of PRKDC mRNA induced by METTL3 contributed to anlotinib resistance in osteosarcoma." (PMID 39924638, 2025). "Thus, targeting METTL3/PRKDC may be a novel strategy for improving therapeutic efficacy in human osteosarcoma." (PMID 39924638, 2025). "RIP assays demonstrated that YTHDF1 bound directly to PRKDC mRNA in MG63 cells and human osteosarcoma tissues." (PMID 39924638, 2025). "On the whole, this research revealed a new function for METTL3 in anlotinib resistance in osteosarcoma, demonstrating that METTL3 enhances DNA‐PKcs expression through m6A methylation of PRKDC mRNA." (PMID 39924638, 2025). "FISH‐IF co‐localisation assay confirmed similar distributions of METTL3 protein and PRKDC mRNA in MG63, U‐2 OS cells, and human osteosarcoma tissues." (PMID 39924638, 2025). "Furthermore, FISH‐IF assays confirmed the co‐localisation of YTHDF1 protein and PRKDC mRNA in MG63 and U‐2 OS cells as well as in human osteosarcoma tissues." (PMID 39924638, 2025). "Remarkably, RNA immunoprecipitation (RIP) assays conducted in MG63 cells and human osteosarcoma tissues revealed significant enrichment of PRKDC in the METTL3 immunoprecipitation group, however, not in IgG control group." (PMID 39924638, 2025). "Notably, we observed m6A modifications in PRKDC mRNA in MG63 and U‐2 OS cells and in human osteosarcoma tissues." (PMID 39924638, 2025). "M6A and PRKDC exhibited co‐localisation in MG63 and U‐2 OS cells and in human osteosarcoma tissues." (PMID 39924638, 2025).
liver cancer (11 papers, 2008 to 2025). An epithelial or non-epithelial malignant neoplasm that arises from the liver. "In this study, we identified three NHEJ genes (FEN1, PRKDC and XRCC6) were upregulated in liver cancer tissue based on TCGA data." (PMID 37016451, 2023).